GPC3 (glypican 3)
Description:
Cell surface proteoglycan. Negatively regulates the hedgehog signaling pathway when attached via the GPI-anchor to the cell surface by competing with the hedgehog receptor PTC1 for binding to hedgehog proteins (By similarity). Binding to the hedgehog protein SHH triggers internalization of the complex by endocytosis and its subsequent lysosomal degradation (By similarity). Positively regulates the canonical Wnt signaling pathway by binding to the Wnt receptor Frizzled and stimulating the binding of the Frizzled receptor to Wnt ligands. Positively regulates the non-canonical Wnt signaling pathway (By similarity). Binds to CD81 which decreases the availability of free CD81 for binding to the transcriptional repressor HHEX, resulting in nuclear translocation of HHEX and transcriptional repression (By similarity). Inhibits the dipeptidyl peptidase activity of DPP4. Plays a role in limb patterning and skeletal development by controlling the cellular response to BMP4 (By similarity). Modulates the effects of growth factors BMP2, BMP7 and FGF7 on renal branching morphogenesis (By similarity). Required for coronary vascular development (By similarity). Plays a role in regulating cell movements during gastrulation (By similarity).
Synonyms: OCI-5; SGBS; SGBS1; SGB; DGSX; GTR2-2; MXR7; SDYS
Tractability: Antibody: a drug acting on it is in phase 2 or 3 trials; UniProt places it where antibodies can reach, with high confidence; its Gene Ontology location is reachable by antibodies, with high confidence; UniProt predicts a signal peptide or a membrane-spanning region; the Human Protein Atlas places it where antibodies can reach. PROTAC: ubiquitination databases record sites on it; its protein half-life has been measured.
Gene: Protein-coding gene on chromosome X (133,535,745 to 133,987,100, reverse strand). Ensembl gene ENSG00000147257.
Subcellular location: Cell membrane
Subcellular location (Human Protein Atlas): Plasma membrane
Pathways (Reactome):
Disease: Attachment and Entry; Defective B3GALT6 causes EDSP2 and SEMDJL1; Defective B3GAT3 causes JDSSDHD; Defective B4GALT7 causes EDS, progeroid type; Defective EXT1 causes exostoses 1, TRPS2 and CHDS; Defective EXT2 causes exostoses 2; Dengue Virus Attachment and Entry; Dengue Virus-Host Interactions; RSV-host interactions; Respiratory syncytial virus (RSV) attachment and entry
Metabolism: Glycosaminoglycan-protein linkage region biosynthesis; HS-GAG biosynthesis; HS-GAG degradation
Hemostasis: Initiation of coagulation cascade; Regulation of clotting cascade
Metabolism of proteins: Post-translational protein phosphorylation; Regulation of Insulin-like Growth Factor (IGF) transport and uptake by Insulin-like Growth Factor Binding Proteins (IGFBPs)
Sensory Perception: Retinoid metabolism and transport
Gene Ontology:
Molecular function: peptidyl-dipeptidase inhibitor activity; protein binding
Biological process: positive regulation of canonical Wnt signaling pathway; regulation of canonical Wnt signaling pathway; regulation of non-canonical Wnt signaling pathway; anatomical structure morphogenesis; cell migration; cell migration involved in gastrulation; cell proliferation involved in kidney development; coronary vasculature development; mesenchymal cell proliferation involved in ureteric bud development; mesonephric duct morphogenesis; negative regulation of smoothened signaling pathway; positive regulation of endocytosis; positive regulation of protein catabolic process; regulation of protein localization to membrane; regulation of signal transduction
Cellular component: plasma membrane; cell surface; endoplasmic reticulum lumen; Golgi lumen; lysosomal lumen; extracellular matrix; lysosome
Gene-disease validity (ClinGen):
ClinGen rates the evidence that GPC3 causes each of these diseases.
Simpson-Golabi-Behmel syndrome (X-linked): Definitive. Simpson-Golabi-Behmel syndrome is a rare X-linked multiple congenital anomalies syndrome, characterized by pre- and postnatal overgrowth, distinctive craniofacial features, variable congenital malformations, organomegaly and an increased tumor risk.
Cancer hallmarks: suppression of growth (promotes); invasion and metastasis (promotes)
Homologues: Orthologues: macaque GPC3 (99% identical), dog GPC3 (96% identical), rabbit GPC3 (95% identical), pig GPC3 (95% identical), rat Gpc3 (94% identical), mouse Gpc3 (94% identical), chimpanzee GPC3 (91% identical), guinea pig GPC3 (85% identical), tropical clawed frog gpc3 (54% identical), zebrafish gpc3 (42% identical), Drosophila melanogaster dally (22% identical), Caenorhabditis elegans gpn-1 (21% identical). Paralogues in human: GPC5 (41% identical), GPC6 (24% identical), GPC4 (22% identical), GPC1 (21% identical), GPC2 (19% identical).
Diseases named in the same sentence as GPC3 in open-access papers:
GPC3 is named in the same sentence as 232 diseases in open-access papers, as found by Europe PMC text mining. Sharing a sentence is not in itself a finding about the gene and the disease. The quoted sentences say what the papers report.
hepatocellular carcinoma (438 papers, 2004 to 2026). A malignant tumor that arises from hepatocytes. "This heightened expression of GPC3 is also significantly linked to poorer prognoses for patients with hepatocellular carcinoma." (PMID 40308592, 2025). "Glypican‐3 (GPC3) is a key diagnostic marker and therapeutic target in hepatocellular carcinoma (HCC), interacting with Wnt and Hippo/YAP pathways related to cancer proliferation." (PMID 40657181, 2025). "Glypican-3 (GPC3) is expressed in a group of solid neoplasms including hepatocellular carcinoma (HCC), the third most common cause of cancer-related death in the world." (PMID 38645165, 2024). "As a coreceptor in Wnt and HGF signaling, glypican-3 (GPC-3) promotes the progression of tumor and is associated with a poor prognosis in hepatocellular carcinoma (HCC)." (PMID 36091074, 2022). "GPC3 is overexpressed in hepatocellular carcinomas tissues, and associates with higher invasion and migration." (PMID 33494442, 2021). "The rs2267531 SNP lies within the promoter of Glypican-3 gene (in Xq26) and the CC/C genotype of which has been correlated with susceptibility and reduced overall survival of patients with hepatocellular carcinoma (HCC)." (PMID 34449663, 2021). "Many studies demonstrated that GPC3 peptide vaccine triggers immune response in the patients with advanced hepatocellular carcinoma and the level of immune response was associated with overall survival." (PMID 32582830, 2020). "GPC3 has been linked to hepatocellular carcinoma and a few other cancers, however, the mechanistic role of GPC3 in cancer development remains elusive." (PMID 31428581, 2019). "Glypican-3 (GPC3) is a glycosylphosphatidylinositol-anchored cell surface protein overexpressed in hepatocellular carcinoma(HCC), and its overexpression is associated with poor prognosis." (PMID 28035063, 2017). "Immunohistochemical studies have suggested that over-expression of GPC3 is associated with a poorer prognosis for hepatocellular carcinoma patients." (PMID 28510121, 2017). "GPC3 upregulation has also been associated with an intensified fibroblast growth factor signaling pathway in hepatocellular carcinomas." (PMID 28978053, 2017). "Increasing evidence suggests soluble GPC3 as a novel diagnostic candidate marker in hepatocellular carcinoma." (PMID 28510121, 2017). "GPC3 is the causative gene for Simpson-Golabi Behmel Syndrome and is strongly up-regulated in hepatocellular carcinoma." (PMID 24244720, 2013). "GPC3 has also been implicated in sporadic cancer, particularly hepatocellular carcinoma, for which it has been shown to be a useful diagnostic marker." (PMID 20868507, 2010). "For instance, multifunctional nanoparticles targeting GPC3, a proteoglycan associated with hepatocellular carcinoma (HCC), have shown enhanced cellular uptake in GPC3-positive HCC cells, highlighting their potential for targeted drug delivery and imaging applications." (PMID 40421114, 2025). "Glypican-3 (GPC3) is a tumor associated antigen expressed by hepatocellular carcinoma (HCC) cells." (PMID 33580090, 2021). "Glypican-3 (GPC3) is an attractive diagnostic marker for hepatocellular carcinoma (HCC)." (PMID 34439132, 2021). "GPC3 expression is upregulated in liver cancer, and has been suggested as a diagnostic biomarker and as a potential target for cancer immunotherapy in hepatocellular carcinoma." (PMID 31956905, 2020). "The hepatocellular carcinoma cells positive to both GPC3 and cytokeratin 19 were found to have the highest risk of multifocality, microvascular invasion, regional lymph node involvement, shortest recurrence time, and distant metastasis in a retrospective study of immunohistochemical staining." (PMID 28510121, 2017). "Recent studies show that GPC3 is associated with the development and presence of hepatocellular carcinoma (HCC), and might serve as an auxiliary diagnostic marker for the disease." (PMID 28852111, 2017).
hepatocellular carcinoma (continued). "Glypican-3 (GPC3), an oncofetal antigen re-expressed in a high frequency of neoplastic hepatocytes has emerged as a useful immunohistochemical diagnostic test and potential biomarker for hepatocellular carcinoma." (PMID 22564378, 2012). "GPC3 is a member of the glypican family of glucosyl-phosphatidylinositol-anchored cell-surface heparin sulfate proteoglycans and is well established as a serologic and immunohistochemical diagnostic tool for hepatocellular carcinomas in man." (PMID 20167095, 2010). "Immunohistochemical staining, particularly with markers such as HSP70, glypican-3 (GPC3), and glutamine synthetase (GS), provides additional diagnostic specificity, with positivity for at least two markers strongly supporting the diagnosis of hepatocellular carcinoma." (PMID 40831827, 2025). "As we know, the gene expression profile of OCCC is similarly to renal clear cell carcinoma (RCC) and hepatocellular carcinoma (HCC), and GPC3 is an established diagnostic marker for HCC." (PMID 38824600, 2024). "PCR analysis of 17 genes revealed GPC3 as the most significantly differentially expressed gene.GPC3 is a membrane-associated proteoglycan that is specifically up-regulated in hepatocellular carcinoma (HCC)." (PMID 39777330, 2024). "Aberrant GPC3 expression is implicated in tumorigenesis, and GPC3-positive cancers including hepatocellular carcinomas (HCC), are characterized by a highly metabolic and immunosuppressive landscape, and exhaustion is a common feature of tumor-resident T cells." (PMID 35507536, 2022). "Glypican 3 (GPC3) is a valuable diagnostic marker and a potential therapeutic target in hepatocellular carcinoma (HCC)." (PMID 25625609, 2015). "Glypican-3 (GPC3) is a cell surface-associated HSPG that is highly expressed in hepatocellular carcinoma (HCC)." (PMID 26332121, 2015). "Glypican-3 is overexpressed in hepatocellular carcinoma (HCC) and a valued serum diagnostic marker of the disease." (PMID 23984412, 2013). "Such a construct simultaneously targets glypican-3-positive hepatocellular carcinoma cells and blocks the CD47-SIRP-α axis, thereby promoting macrophage engagement and phagocytosis." (PMID 42318525, 2026). "Histology confirmed hepatic carcinosarcoma (pT4), comprising cholangiocarcinoma (CK7, BerEP4+), hepatocellular carcinoma (Glypican-3+), and squamous carcinoma (p63, p40+)." (PMID 41695364, 2026). "As alternatives, several studies have proposed novel targets like glypican-3 (GPC3) in hepatocellular carcinoma and prostate-specific membrane antigen (PSMA) in prostate cancer." (PMID 41601679, 2026). "Building on this molecular design, BTOGP‐GPC3 nanoparticles (NPs) are further developed by conjugating the hepatocellular carcinoma (HCC)‐specific targeting molecule Glypican‐3 peptide (GPC3)." (PMID 41313254, 2026). "Glypican-3 (GPC3)-targeted chimeric antigen receptor T (CAR-T) cell therapy is a promising approach for hepatocellular carcinoma (HCC), but marked interpatient variability and antigen heterogeneity limit its broader application." (PMID 42121900, 2026). "Analysis of tissues from 30 patients with hepatocellular carcinoma revealed concomitant upregulation of HBx and GPC3 in tumour specimens." (PMID 41958083, 2026). "Glypican-3 (GPC3) is an oncofetal protein widely being explored as a diagnostic and therapeutic target in hepatocellular carcinoma (HCC)." (PMID 42182336, 2026). "An mRNA–LNP platform for hepatic expression of a bispecific IFN-α/anti-GPC3 protein showed significant antitumor activity against GPC3-positive hepatocellular carcinoma by enhancing CD8+ T-cell infiltration and synergizing with anti-PD-1 therapy." (PMID 41262250, 2025). "Our immunohistochemical analysis has shown that GPC3 is expressed in many hepatocellular carcinomas, but the expression pattern on the cell membrane is rare." (PMID 40076777, 2025).
hepatocellular carcinoma (continued). "Codrituzumab (GC33), an anti-GPC3 mAb, has been treated in advanced hepatocellular carcinoma (HCC) patients in a phase I clinical study." (PMID 40688491, 2025). "In hepatoma, GPC3 is detected on the surface and anchored to the cell membrane via a glycophosphatidylinositol linkage, making GPC3 a favourable target for CAR‐T cell therapy." (PMID 41267637, 2025). "In a preclinical study, a novel CAR-T cell therapy targeting glypican-3 (GPC3), a protein highly expressed in hepatocellular carcinoma, was investigated." (PMID 39805063, 2025). "In hepatocellular carcinoma, both antibody-mediated targeting of GPC3 and chimeric antigen receptor T-cell (CAR-T) therapy directed against GPC3 have demonstrated efficacy in suppressing WNT signaling." (PMID 40650246, 2025). "In conclusion, GPC3 is a promising target for treating hepatocellular carcinoma (HCC) due to its selective overexpression in cancer cells." (PMID 40416124, 2025). "have demonstrated that iPSC-derived CAR-expressing ILC/NK-like cells can effectively target glypican-3 (GPC3) in hepatocellular carcinoma and CD19 in B-cell malignancies." (PMID 40963622, 2025). "Although GPC3 in hepatocellular carcinoma stains cytoplasm, we were able to establish a system for simultaneously staining six membrane proteins." (PMID 40076777, 2025). "In another example, Shi labeled a humanized anti-GPC3 monoclonal antibody with ICG to create a NIR-II fluorescent probe (GPC3-ICG) designed to specifically target hepatocellular carcinoma (HCC)." (PMID 39776802, 2025). "Flow cytometry assessed BsAb binding to A431 (CD16A-/GPC3-), GPC3+ hepatocellular carcinoma (HCC) lines (HepG2, Huh7, Hep3B), A431-GPC3 (G1), PBMCs, and A431-CD16A cells." (PMID 40574860, 2025). "ROBO1, like GPC3, has been identified as a membrane protein frequently expressed in hepatocellular carcinoma." (PMID 40076777, 2025). "Upon expansion, these anti–glypican-3 CAR Vδ1 cells exhibited minimal inhibitory receptor expression manifested by robust in vitro anti-tumor activity against hepatocellular carcinoma cells, even when in the presence of soluble glypican-3." (PMID 40148988, 2025). "These OMVs where then loaded to glypican-3-targeting macrophages, a significant molecule in melanoma and hepatocellular carcinoma, and used to treat mice bearing H22 hepatocellular carcinomas." (PMID 40292310, 2025). "This has been proposed as a disease mechanism in both hepatocellular carcinoma as well as osteosarcoma, where GPC3 is also highly expressed." (PMID 40650246, 2025). "Notable investigational agents include the following: RAYZ-8009 (DOTA-RYZ-GPC3), targeting glypican-3 in hepatocellular carcinoma, and 177Lu-FAP-2286, directed against fibroblast activation protein (FAP) in stromal-rich tumours." (PMID 40725089, 2025). "A promising molecular target in hepatocellular carcinoma (HCC) is glypican-3 (GPC3), a cell-surface heparan sulfate proteoglycan that shows minimal expression in normal tissues but significant overexpression in 70–80% of HCC cases." (PMID 40725089, 2025). "In hepatocellular carcinoma, the abTCR recognizes alpha-fetoprotein presented by HLA-A*02, while a second chimeric receptor, consisting of a GPC3-specific scFv fused to CD28, delivers additional stimulation." (PMID 40481182, 2025). "GPC3 is frequently expressed in hepatocellular carcinoma and hepatoblastoma, but it is often expressed in the cytoplasm, and this study also revealed that it is expressed on the cell membrane less frequently." (PMID 40076777, 2025). "Several studies have attempted to engineer CAR-T, NK, and M cells targeting specific antigens in hepatocellular carcinoma, such as glypican-3 (GPC3), showing promising initial results; however, further improvements and optimizations are necessary." (PMID 40308592, 2025). "As a result of binding to Wnt signaling proteins and growth factors, GPC3 plays an important role in Hepatocellular Carcinoma progression." (PMID 40296906, 2025).